Y_RNA (Y RNA )
Gene: Miscellaneous RNA gene on chromosome 2 (222,404,985 to 222,405,095, forward strand). Ensembl gene ENSG00000200822.
Homologues: Orthologues: chimpanzee Y_RNA (98% identical), macaque Y_RNA (90% identical). Paralogues in human: Y_RNA (85% identical), RNY1 (84% identical), Y_RNA (84% identical), Y_RNA (83% identical), Y_RNA (82% identical), RNY1P11 (81% identical), Y_RNA (81% identical), RNY1P8 (80% identical), Y_RNA (80% identical), RNY1P10 (79% identical), Y_RNA (79% identical), Y_RNA (78% identical), and 96 more.